PPARG (peroxisome proliferator activated receptor gamma)
Diseases named in the same sentence as PPARG in open-access papers (continued):
Sharing a sentence is not in itself a finding about the gene and the disease.
Insulin resistance (continued). "Overall, our findings convincingly demonstrate that PPARG Pro12Ala –IRS1 Gly972Arg interactions, PPARG Pro12 and susceptibility to environmental factors might modulate the relationship between insulin resistance and type 2 diabetes in this population." (PMID 24447396, 2014). "Genetic techniques of inhibiting PPARγ’s phosphorylation could improve insulin resistance and increase adiponectin level." (PMID 23342006, 2013). "Previous studies have shown that the inhibition of PPARγ could reduce fat and body weight and improve insulin resistance via the modulation of genes related to lipid and glucose metabolism." (PMID 23533476, 2013). "Thus, the activity of InsR, IRS, PI3K, and PPARγ is important in mediating the metabolic effects of insulin and closely correlative with insulin resistance." (PMID 23762123, 2013). "PPARγ is expressed at low levels in the liver but is upregulated in rodent fatty livers, contributing to hepatic triglyceride accumulation with a protective effect to dyslipidemia and insulin resistance in other tissues." (PMID 23346097, 2013). "We couldn’t find significant correlation between HOMA-IR as an insulin resistance index and PPARγ and measured adipokines level in our study (pvalue >0.05)." (PMID 24330836, 2013). "Only the role of PPARγ in DR pathogenesis has been elucidated mainly because of the protein’s role in vascular permeability, inflammation, angiogenesis, neovascularization, and insulin resistance, all of which contribute to the onset and severity of DR." (PMID 23559865, 2013). "PPARγ agonists have been studied in the past; they were given as treatments both in vitro and in vivo, resulting in normalised serum insulin and glucose concentrations in insulin-resistance models." (PMID 24324517, 2013). "Elevated PPARγ expression in skeletal muscle increases insulin sensitivity, and knockout of PPARγ in skeletal muscle using a Cre-loxP system results in glucose intolerance and insulin resistance." (PMID 23818907, 2013). "Moreover, novel PPARγ agonists acting mainly on adipose PPARγ prevent formation of steatotic livers in mice by improving insulin resistance, upregulating adiponectin, and downregulating leptin expression and secretion." (PMID 23346097, 2013). "Here, we show that extract of wax gourd peel (EWGP) may prevent the development of hyperlipidemia and insulin resistance in high-fat diet-fed C57BL/6 mice via inhibition of the transactivities of PPARγ and reduction in the expression of its downstream genes." (PMID 23533476, 2013). "By reducing insulin resistance in the kidney and improving glycaemic control, PPARγ activation may indirectly improve renal function." (PMID 22448165, 2012). "Together our findings indicate that high FFA and low PPARγ levels could enhance the recruitment of inflammatory macrophages into adipose tissue, contributing to the development of tissue inflammation and insulin resistance." (PMID 22529965, 2012). "It is also clinically important to investigate the possibility that crosstalk between AT2 receptor stimulation and PPARγ activation may regulate adiopocyte function and insulin resistance, and therefore we also examined this possibility in this study." (PMID 23155382, 2012). "Besides IRS1 rs2943634 the group of insulin resistance SNPs consisted of PPARG rs1801282, GCKR rs780094, GCKrs1799884, and IGF1rs35767." (PMID 23101478, 2012). "In macrophages PPARG is also involved in the control of cholesterol metabolism and low or absent PPARG expression is associated with increased atherosclerosis and insulin resistance." (PMID 23118933, 2012). "Our data showed that telmisartan improved the levels of blood glucose, which might indicate that telmisartan functioned as a PPARγ agonist and improved insulin resistance in Akita mice." (PMID 22319521, 2012). "PPARγ agonists have been studied for potential use in the prevention of insulin resistance." (PMID 22726273, 2012).
Insulin resistance (continued). "On the other hand, the reduced SREBF1 expression could also decrease lipogenesis in smaller adipocytes and hinder adipocyte differentiation via PPARG down-regulation, leading to increased insulin resistance." (PMID 22471940, 2012). "The final comparison that we have analyzed was between POKO and ob/ob islets, representing different states of insulin resistance that could identify PPARγ-dependent genes involved in expansion and function of β-cell." (PMID 22208362, 2011). "The nuclear receptors peroxisome proliferator-activated receptor γ (PPARγ) and peroxisome proliferator-activated receptor δ (PPARδ) play central roles in regulating metabolism in adipose tissue, as well as being targets for the treatment of insulin resistance." (PMID 21843327, 2011). "Moreover, vitamin D directly regulates the metabolism of FFAs by means of its action on peroxisome proliferator-activated receptor gamma (PPAR-γ) improving FFA-induced insulin resistance in vitro." (PMID 21749681, 2011). "PPARγ agonists are a class of drugs used against insulin resistance and T2D." (PMID 20508722, 2010). "Therefore, PPARγ antagonist inhibited the function of fish oil as a strong PPARγ stimulator, and increased large adipocytes and induced insulin resistance." (PMID 20846400, 2010). "Impaired SREBP-1 nuclear penetration may inhibit the activation of PPARγ or related adipogenic transcription factorsthus leading to defective adipogenesis and insulin resistance." (PMID 19125203, 2009). "Defective SREBP-1c signaling may explain the decreased differentiationand insulin resistance of PI-treated cells and the ability of PPARγ agonists to overcome the PI effects on fatcell differentiation and insulin response." (PMID 19125203, 2009). "In summary, activation of PPARγ improves adipose tissuefunction by having a beneficial effect on the adipocyte—macrophagerelationship, which may result in prevention of insulin resistance." (PMID 19081837, 2009). "In that pedigree, severe insulin resistance was restricted to individuals who were doubly heterozygous for the PPP1R3A FS variant and an unlinked loss-of-function mutation in PPARG (AAA553T; stop codon 186), which encodes a key transcriptional regulator of adipocyte differentiation." (PMID 18232732, 2008). "However, in animal models of insulin resistance and fatty livers, the hepatic expression of PPARγ is markedly increased." (PMID 18822121, 2008). "One of these new generation compounds could prevent adipogenesis,insulin resistance, and obesity by blocking endogenous ligand-inducedactivation of PPARγ.In addition, these compounds may increase glucose disposal in peripheraltissues." (PMID 18317516, 2007). "However, many crucial aspects of the molecularmechanism by which modulation of PPARγ activityaffects insulin resistance and glucose homeostasis are stillnot clearly understood." (PMID 15203881, 2004). "PPARγ agonists ameliorate insulin resistance and dyslipidemia in type 2 diabetic patients." (PMID 15491498, 2004). "Pre-clinical evidence in mice suggests that Metrnl expression in adipocytes may improve insulin sensitivity via the activation of the peroxisome proliferator-activated receptor gamma (PPARγ) pathway, which is crucial for managing insulin resistance and adipocyte differentiation." (PMID 40559404, 2025). "Thus, PPARγ activation may be involved in orange juice-induced improvement in insulin resistance and dyslipidemia while reducing inflammation and preventing metabolic syndrome." (PMID 40137162, 2025). "Additionally, upregulation of PPARG may counteract oxidative stress and insulin resistance in the brain." (PMID 41282094, 2025). "Similarly, a reduction in PPARG expression indicates insulin resistance, as PPARG is the main regulator of sensitivity to insulin, but also suggests disturbances in lipid homeostasis, which may lead to lipotoxicity." (PMID 40806527, 2025).
Insulin resistance (continued). "Finally, PPARγ, which is mainly expressed in the adipose tissue, immune cells, and colon, is the master gene of adipocyte differentiation and plays a significant role in controlling insulin resistance and energy homeostasis." (PMID 39199386, 2024). "Pioglitazone, a well-tolerated FDA-approved thiazolidinedione (TZD) and PPARγ-agonist, demonstrates a high affinity for both PPARγ isoforms (1 and 2), which are expressed in both humans and mice, and is indicated for the treatment of insulin resistance in type-2 diabetes mellitus." (PMID 39518077, 2024). "The clinical efficacy of Pioglitazone in our patient could not be explained by the decrease in insulin resistance alone, but might be related to molecular interaction between Pioglitazone and the mutant PPARγ gene, at least in this case of a c.1024C>T variant." (PMID 39596129, 2024). "Interestingly, the downregulation of PPARα and PPARγ, such as the one we highlighted in our model, could be related to the accumulation of lipid droplets within hepatocytes, also contributing to the insulin resistance reported in DS individuals." (PMID 38942607, 2024). "Phosphorylation at Ser273 is linked with the development of insulin resistance in mice; however, PPARγ protein degradation has not been associated with phosphorylation at these sites and cadmium did not promote phosphorylation of PPARγ at Ser273." (PMID 36928191, 2023). "Therefore, it is plausible that increased expression of CCN5 could inhibit PPARγ and subsequently contribute to insulin resistance and diabetes through the formation of an additional complex with Zfp423." (PMID 37794318, 2023). "Therefore, Rb1 might affect macrophage activation through PPARγ, which might alleviate obese insulin resistance in T2D early stage." (PMID 37049846, 2023). "Additionally, the decreased phosphorylation of IRS1 increased expression of PPARγ and reduced phosphorylation of NF-κB could be attributed to the attenuation of insulin resistance of vitamin D3." (PMID 37324274, 2023). "In addition, our previous studies verified that the activation of PPARγ could alleviate obese insulin resistance with the IRS-1 insulin metabolic pathway in vivo and in vitro." (PMID 37049846, 2023). "Moreover, the activation of peroxisome proliferator-activated receptor gamma (PPAR-γ) by lipid metabolites could also play a pivotal role in changes in bone in patients with insulin resistance and T2DM." (PMID 37047445, 2023). "Network pharmacology analysis showed that some popular metabolic targets for the FDA-approved antidiabetic drugs, such as PPARG and PPARA, the targets of pioglitazone, might play a great role in MA activity against insulin resistance and dyslipidemia associated with T2DM." (PMID 36160451, 2022). "Likewise, AST may modulate peroxisome proliferator-activated receptor gamma (PPAR-γ) with ameliorative effects on insulin resistance." (PMID 35056816, 2022). "On focusing to recognize the cellular mechanism of miR-27a that causes insulin resistance in skeletal muscle, the attention was directed towards peroxisome proliferator activated receptor gamma (PPARγ) since miR-27a has been shown as a negative modulator of it." (PMID 35590121, 2022). "PPARγ activation by glitazones could reduce insulin resistance and dyslipidemia." (PMID 36387870, 2022). "In addition, administration of naringen into a diabetic 53-year-old African American female (a case study) showed that naringenin exerted its regulatory effects on insulin resistance and metabolic rate via activation of PPARα and PPARγ, leading to promotion of UCP1 and CPT1β." (PMID 36092543, 2022). "Therefore, the induction of PPARγ by curcumin could regulate glucose homeostasis and insulin resistance and also suppress inflammatory cytokines (including nuclear factor-κB (NF-κB) and matrix metalloproteinases (MMPs)) in macrophages and oxidative stress." (PMID 36092543, 2022).
Insulin resistance (continued). "Furthermore, quercetin may exert its antidiabetic and glucose uptake effects through activating SIRT1/ PPARγ/AMPK signal cascades to improve the complications of insulin resistance and diabetes." (PMID 36092543, 2022). "In addition, PPARG plays an important role in the process of insulin resistance." (PMID 35207731, 2022). "Moreover, a second study conducted on Romanian and Moldavian children underlined the lack of clinical impact of PPARG gene polymorphism on insulin resistance among an overweight population sample." (PMID 36466447, 2022). "Furthermore, activation of this pathway was found to reduce expression of insulin receptor substrate-1 (IRS1) and PPARγ in mature human adipocytes and in hypertrophic adipocytes from ob/ob mice, thus contributing to adipocyte dysfunction and insulin resistance." (PMID 35769086, 2022). "Therefore, targeting PPARG and appropriately increasing its expression may serve as a therapeutic target, with great potential to break the positive feedback loop of insulin resistance and hyperinflammatory states." (PMID 35669784, 2022). "Similarly, 5 μmol/L morusin also markably inhibited PPARG expression induced by insulin resistance." (PMID 36278175, 2022). "An integrated system pharmacology analysis then revealed that various targets such as PPARG, RELA, EGFR and numerous pathways such as TNF signalling, PI3K-Akt signalling, MAPK signalling and NF-κB signalling were involved in the underlying mechanisms of GQD in improving diabetic insulin resistance." (PMID 36187136, 2022). "In addition to the redistribution of lipids, PPARγ also inhibits the synthesis of tumor necrosis factor α (TNFα) and resistin, both related to inflammation and insulin resistance, while inducing the synthesis of adiponectin, which favors the oxidation of fatty acids." (PMID 33946267, 2021). "In addition, both the murine knockout specific to adipose tissue and the human negative dominant mutation in PPARγ are associated with lipodystrophy and insulin resistance." (PMID 33946267, 2021). "Interference with cell metabolism by Tregs expressing PPARγ could inhibit adipose tissue inflammation in obese patients, and thus, Tregs may become a new target for the prevention and treatment of inflammation and insulin resistance." (PMID 34658891, 2021). "In addition, QC exhibited antiobesity and anti-insulin resistance effects in the adipocytes of obese rats and resulted in the downregulation of peroxisome proliferator-activated receptor gamma (PPAR-γ) mRNA in liver, muscle, and adipose tissue in high-fat diet-induced insulin-resistant rats." (PMID 33669133, 2021). "Upregulation of the peroxisome proliferator-activated receptor gamma (PPARγ) pathway could attenuate inflammation and fibrosis in hepatic tissue as well as insulin resistance, and these had been confirmed by preclinic animal research in vivo or clinic research." (PMID 34659439, 2021). "Dominant-negative mutations in human PPARγ are associated with insulin resistance and T2DM." (PMID 34489979, 2021). "The process of activation of peroxisome proliferator-activated receptor gamma (PPAR-γ) also prevented insulin resistance in T2DM patients by the formation of adipokines, which implies that honey may be helpful in modulating adiponectin mediated by PPAR-γ, thus alleviating insulin resistance." (PMID 33299532, 2020). "Peroxisome proliferator-activated receptor gamma (PPARγ) is the target of clinical insulin sensitizers, which can protect diabetes and related complication, such as endothelial cell injury and vascular endothelial insulin resistance (IR) induced by high glycemic." (PMID 32390845, 2020). "Particularly, insulin resistance is associated with hyperinsulinemia, increased levels of insulin-like growth factors (IGF), and alterations in necrosis factor (NF)-κB and peroxisome proliferator-activated receptor gamma (PPARγ) signaling, which plays a key role in the pathogenesis of CRC." (PMID 32709256, 2020).
Insulin resistance (continued). "Similarly, several basic researches revealed that insulin resistance was reported to be associated with hyperinsulinemia, increased levels of IGF, and alterations in NF-κB and PPARγ signaling, which may play a key role in the pathogenesis of CRC." (PMID 32709256, 2020). "Interestingly, the pharmacological inhibition of PPARγ or genetic inhibition of mitochondrial fatty acid oxidation in macrophages stimulated with SFAs exacerbate inflammation, and PPARγ deletion in macrophages aggravates insulin resistance in mice fed a HFD." (PMID 31068773, 2019). "In conclusion, decitabine combined with UC-MSCs attenuated insulin resistance more effectively and enhanced the anti-diabetic effects of MSCs in T2D mice, and this effect was partially attributed to directing macrophages into M2 phenotype via increasing PPARγ expression." (PMID 31426846, 2019). "Therefore, activation of PPARγ is a possible way to improve insulin resistance and hyperglycemia." (PMID 30258609, 2018). "PPARγ has been heavily studied in part because the availability of its pharmacological agonists (TZDs) ligands, such as rosiglitazone and pioglitazone, both known to improve insulin resistance and exert anti-inflammatory effects in the adipose tissue and on a systemic level." (PMID 30037087, 2018). "Previous study reported that adipocyte Metrnl controls insulin sensitivity through the peroxisome proliferator-activated receptor gamma (PPARγ) pathway and suggested that adipocyte Metrnl is an inherent insulin sensitizer and may be a therapeutic target for insulin resistance." (PMID 29854769, 2018). "Thus, we hypothesized that insulin resistance-associated genes, namely the ADAMTS9, GCKR, and PPARG genes, may be linked with cognitive aging." (PMID 28225792, 2017). "Consequently, we investigated whether PPARγ activation is related in APL-induced insulin resistance improvement in palmitate -treated L6 myotubes." (PMID 27391974, 2016). "In conclusion, participation in an 8 week, moderate-intensity exercise programme induces M2 marker expression and PPARγ activation in monocytes (potentially priming them for differentiation into M2-polarised tissue macrophage) and exerts beneficial systemic effects with regard to insulin resistance." (PMID 27339155, 2016). "Therefore, inactivation of insulin/PPARγ pathway in epididymal fat tissue by aliskiren may reduce fat mass and adipocyte hypertrophy, thereby contributing to a decrease in body weight and insulin resistance." (PMID 26732252, 2016). "In adipocytes, PPARγ not only promotes the removal of lipids and free fatty acids (FFAs) but also inhibits the production of proinflammatory cytokines, ameliorating insulin resistance; this finding suggests that Ppm1b and other genes may be worth further study under certain conditions." (PMID 27846294, 2016). "It thus seems likely that insulin resistance and defective insulin delivery to the circulation may combine to produce especially severe glucose intolerance in PPARγ-/F:MORE+/Cre neonates and that this combination of defects does not persist in those animals that survive to adulthood." (PMID 27505464, 2016). "PPARγ may have dual roles in regulating insulin resistance, at least in experimental mice." (PMID 26074951, 2015). "In light of these data and our finding that TUSC5 regulates insulin-stimulated glucose transport in adipocytes, we hypothesized that TUSC5 expression may be reduced in insulin resistance and that PPARγ agonists may work in part by restoring TUSC5 expression levels." (PMID 26240143, 2015). "We observed that neither IRS1 972Arg allele nor PPARG 12Ala were associated with type 2 diabetes or insulin resistance/sensitivity, but in a model containing both the alleles and their interaction term, the presence of the PPARG Pro12 conferred a 64% risk of prevalent type 2 diabetes." (PMID 24447396, 2014).